ALDH2 (aldehyde dehydrogenase 2 family member)
Diseases named in the same sentence as ALDH2 in open-access papers (continued):
Sharing a sentence is not in itself a finding about the gene and the disease.
myocardial infarction (continued). "In another study, ALDH2 activation by Alda-1 ameliorated ischemia or reperfusion injury in vivo, suggesting that ALDH2 activator compounds may be useful to patients with acute myocardial infarction, cardiac bypass surgery or heart transplantation." (PMID 28205523, 2017). "Therefore, ALDH2 plays a key role in myocardial infarct size and cardiomyocyte apoptosis, and ALDH2 activation confers cardioprotection." (PMID 27148058, 2016). "Several surveys, including studies conducted in Japan, China and Korea, have indicated that the ALDH2 Glu504Lys polymorphism is closely associated with myocardial infarction and/or ACS in East Asians and the ALDH2 mutant genotypes (*1/*2 and *2/*2) are considered independent risk factors of ACS." (PMID 27191745, 2016). "Till now, there is no report exploring the association between ALDH2 gene methylation and myocardial infarction." (PMID 25629048, 2015). "In contrast, myocardial infarction was significantly increased in ALDH2 *2 carriers compared with that in ALDH2 *1/*1 abstainers (odds ratio [95% CI]: *1/*1 abstainers as the referent, 2.63 [1.28–6.13] in abstainers with *2, 1.89 [0.89–4.51] in *1/*1 drinkers, 2.35 [1.06–5.79] in drinkers with *2)." (PMID 26599441, 2015). "A meta-analysis of 9 studies that included 1,700 CAD patients and 4,081 healthy controls suggested that ALDH2 Glu504Lys polymorphism may be associated with increased risk of CAD and myocardial infarction in East Asians, especially among Chinese and Korean populations." (PMID 25380998, 2014). "Upregulation of cellular ALDH2 activity can markedly reduce cytotoxic aldehydes and efficiently inhibit cardiac injury as well as significantly limit infarction size during cardiac ischemia in mouse models of myocardial infarction (MI) that can be reversed by the inhibition of ALDH2." (PMID 36694633, 2023). "In conclusion, the data from this study suggest that HSPA8, in conjunction with ALDH2, could regulate fibroblast senescence after oxygen-glucose deprivation, providing a new direction and foundation for effectively intervening in fibroblast senescence after myocardial infarction." (PMID 38247467, 2023). "We hypothesized that DNA methylation may actively participate in the pathogenesis of myocardial infarction and is related to ALDH2 decrease after MI." (PMID 25629048, 2015). "We thus hypothesized that DNA methylation may affect ALDH2 expression in myocardial infarction (MI)." (PMID 25629048, 2015). "BSP analysis showed that DNA methylation did not affect ALDH2 core promoter in the setting of myocardial infarction." (PMID 25629048, 2015). "Furthermore, enhanced activation of ALDH2 could ameliorate myocardial ischemia injury in rats with experiment myocardial infarction (MI)." (PMID 25629048, 2015). "Besides methylation changes of ALDH2 after myocardial infarction, there might be a series of genes, which would also face methylation changes in the setting of MI." (PMID 25629048, 2015). "Serum miR-34a levels in acute myocardial infarction (AMI) patients and rats were significantly higher than healthy subjects and sham rats, which could promote cardiomyocyte apoptosis via negatively regulating ALDH2." (PMID 35265142, 2022).
Stroke (46 papers, 2014 to 2026). Sudden impairment of blood flow to a part of the brain due to occlusion or rupture of an artery to the brain. "Consistent with previous studies, in our cohort, heavy drinking was often accompanied by cigarette smoking, a major vascular risk factor, which can synergistically increase stroke risk across all ALDH2 genotypes." (PMID 41324337, 2026). "Sex‐specific effects of ALDH2 polymorphisms on stroke risk have been consistently observed in previous studies." (PMID 41324337, 2026). "Nonetheless, direct evidence linking the interaction between ALDH2*2 and alcohol consumption to ischemic stroke has been limited—largely because relatively few stroke patients with the ALDH2*2 variant engage in heavy drinking." (PMID 41324337, 2026). "Our study demonstrated that, in a Taiwanese cohort of men with ischemic stroke, carriers of the ALDH2*2 variants who reported heavy drinking had a younger age at stroke onset, suggesting a harmful gene–environment interaction." (PMID 41324337, 2026). "Increasing epidemiological evidence suggests a close association between ALDH2 gene polymorphisms and increased cardiovascular risk factors and stroke incidence." (PMID 40026415, 2025). "Epidemiological surveys have shown that ALDH2 gene polymorphisms are strongly linked to an increased incidence of stroke and cardiovascular risk factors." (PMID 37006480, 2023). "PKCε was also shown to regulate ALDH2 in upstream protection against stroke, as ALDH2 knockdown rats demonstrated a loss in neuroprotective effects, but the overexpression of PKCε increased ALDH2 by 44% and decreased infarct by 33%." (PMID 36358905, 2022). "Aldehyde dehydrogenase 2 (ALDH2) polymorphisms are related to both stroke risk and alcohol consumption." (PMID 34257742, 2021). "We examined the relationship between genetic polymorphisms of ADH1B rs1229984, ALDH2 rs671, and stroke in relation to alcohol consumption among Taiwanese adults." (PMID 34051793, 2021). "Polymorphic variants of Aldehyde dehydrogenase 2 (ALDH2) were found to be associated with alcoholic cardiomyopathy and stroke, and hypertensive male carriers of rs671 in the ALDH2*1/*1 genotype were more likely to have CMBs than ALDH2 *2 allele carriers." (PMID 33352859, 2020). "Previous work has shown an association between higher expression of ALDH2 and lower incidence of stroke in rats." (PMID 32047268, 2020). "This is emphasized by the fact that only two genes histone deacetylase 9 (HDAC9) and ALDH2, are predicted to have AS in all three causes of stroke (CE, LVD, and SVD) in either male or female patients." (PMID 33193047, 2020). "Recently, a meta-analysis of GWAS has been found a tight association between ALDH2 genetic variations and pathogenesis of stroke from Asian decedents." (PMID 29254215, 2017). "From some studies, we detected the genes encoding the enzymes which metabolize aldehyde dehydrogenase 2 (ALDH2) exists polymorphism association with stroke in the pathogenesis process." (PMID 29254215, 2017). "The ALDH2 rs671 polymorphism has the potential to define the risk factors and to individualize stroke treatment before the onset of epilepsy." (PMID 25313998, 2014). "Using a case-control study, we demonstrated that the functional SNP rs671 of ALDH2 is associated with post-stroke epilepsy." (PMID 25313998, 2014). "In this investigation, we first performed a case-control study to explore the potential association of ALDH2 rs671 polymorphism and post-stroke epilepsy (PSE)." (PMID 25313998, 2014). "We evaluated the associations between ALDH2*2 and alcohol consumption with age at stroke onset." (PMID 41324337, 2026). "Additionally, studies have indicated that the ALDH2*1 allele appears to be a significant risk factor for ischemic stroke, multiple lacunar infarction, and stroke in Asian populations." (PMID 37006480, 2023).
Stroke (continued). "For the two behavioral traits, we found that a long region (~2 Mbp) crossing the ALDH2 gene on chromosome 12 (lead SNP rs671) was strongly associated with heavy drinking behavior (> 20 g/day) among the stroke patients (rs671-G, OR = 3.18, 95% CI = 2.83–3.59, MAF = 0.16, P = 2.43 × 10–83)." (PMID 37479695, 2023). "However, in the Bayesian colocalization analysis, there was insufficient evidence to show the abundance of ALDH2 and stroke shared common causal variants (PPH4 < 75%)." (PMID 35449099, 2022). "The ALDH2 Glu504Lys mutant allele has a high-frequency distribution in East Asian populations and has been demonstrated to be associated with an increased risk of cardiovascular disease, stroke, and tumors." (PMID 36939783, 2021). "In addition, the role of the ALDH2 Glu504Lys variant in stroke and tumors is attracting increasing attention." (PMID 36939783, 2021). "Furthermore, ALDH2 overexpression significantly suppressed stroke-induced mitochondria-associated apoptosis and inhibited p-JNK activation and p-JNK/caspase-3 complex formation." (PMID 32210721, 2020). "In general, these findings indicate that ethnic differences among the ALDH2 gene variants may affect the development of stroke in different populations." (PMID 29254215, 2017). "Given that ALDH2 can barely be detected in the blood of patients, the plasma levels of 4-HNE and the presence of the ALDH2 rs671 polymorphism might be two feasible and reliable indexes to evaluate stroke patients for PSE susceptibility." (PMID 25313998, 2014). "Additionally, ALDH2 polymorphisms might influence stroke risk and progression via mechanisms beyond alcohol metabolism." (PMID 41324337, 2026). "Thus, identifying subgroups at high risk of early‐onset stroke, such as ALDH2*2 carriers with heavy drinking, could inform targeted prevention strategies." (PMID 41324337, 2026). "Therefore, this genetic ALDH2 variant is a serious threat to the health of East Asian and Asian populations, and it may be strongly associated with higher stroke and cardiovascular disease mortality in Asians." (PMID 36939783, 2021). "Our data revealed that patients in the ALDH2 wild-type genotype group were significantly more likely to have higher MoCA scores than patients in the mutant and heterozygous genotype group, which suggests that the ALDH2∗2 polymorphism is associated with cognitive impairment after stroke." (PMID 34257742, 2021). "Therefore, in stroke patients, especially in individuals with the ALDH2*2 allele, ALDH2 activation could be a useful strategy to treat or to prevent PSE." (PMID 25313998, 2014). "Multivariable linear regression analyses of stroke onset age according to ALDH2 genotype and alcohol consumption." (PMID 41324337, 2026). "The resulting plot revealed nonparallel slopes and a crossover pattern, supporting the presence of a gene–environment interaction between ALDH2*2 carriage and heavy drinking in determining age at stroke onset." (PMID 41324337, 2026). "Given the high prevalence of ALDH2*2 in East Asians and its influence on drinking behavior (and related habits such as smoking), clarifying this gene–environment interaction may help identify subgroups at heightened risk for earlier onset stroke and inform genotype‐informed prevention strategies." (PMID 41324337, 2026). "Nevertheless, this study provides a solid foundation for the future research on ALDH2 activators used in the treatment of stroke." (PMID 40733191, 2025). "This study lays a good foundation for the future research on ALDH2 activators used in the treatment of stroke." (PMID 40733191, 2025). "Together, these data provide evidence supporting the idea that 4-HNE and its regulating molecule ALDH2 can serve as potential biomarkers for stroke." (PMID 36358905, 2022). "In prior studies, it was observed that stroke-prone, spontaneously hypertensive rats (SHR-SP) were deficient in ALDH2, leading to decreased neuroprotection." (PMID 36358905, 2022).
Stroke (continued). "ALDH2 reportedly has protective properties on myocardial damage, stroke, and diabetic retina damage." (PMID 34439969, 2021). "We evaluated the association of stroke with genetic polymorphisms in the alcohol metabolizing genes, alcohol dehydrogenase 1B (ADH1B, rs1229984) and aldehyde dehydrogenase 2 (ALDH2, rs671) genes based on alcohol consumption." (PMID 34051793, 2021). "The resultant activity of ALDH2 is able to protect against ischemic reperfusion injury, heart failure, stroke, and myocardial infarction in animal models." (PMID 33597876, 2020). "Although JNK is activated while ALDH2 is inhibited after suffering from stroke, the direct relationship between activated JNK and ALDH2 has not been examined." (PMID 32210721, 2020). "The fact that activation of ALDH2 decreases 4-HNE adducts has also been reported in stroke and has been proposed as a strategy for treating or preventing ischemia." (PMID 30131474, 2018). "Overexpression or activation of ALDH2 conferred neuroprotection via clearance of 4HNE, whereas ALDH2 knockdown mitigated the neuroprotective property of protein kinase C in the pathogenesis of stroke." (PMID 27148058, 2016). "Because ALDH2 plays a role in alcohol consumption and moderate ethanol administration is beneficial for protecting against stroke, we divided the subjects into two subgroups according to their history of alcohol consumption." (PMID 25313998, 2014). "Across all ALDH2 genotype groups, women consistently had a later stroke onset than men." (PMID 41324337, 2026). "In a Taiwanese cohort of 930 patients with first‐ever ischemic stroke, we examined whether ALDH2 rs671 (ALDH2*2) and alcohol consumption interact to influence age at stroke onset." (PMID 41324337, 2026). "Given the high prevalence of the ALDH2*2 genotype in East Asians, our findings might be useful for the stroke prevention strategies tailored to this population." (PMID 41324337, 2026). "In contrast, ALDH2*2 carriers with heavy drinking exhibited the earliest stroke onset." (PMID 41324337, 2026). "In addition, ALDH2 attenuates reactive aldehydes and mitochondrial ROS both in vivo and in vitro, protecting against myocardial, pulmonary, hepatic events, and stroke." (PMID 36670098, 2023). "In the stroke model of middle cerebral artery occlusion/reperfusion in rats, they demonstrated a significant downregulation of ALDH2 expression at 2∼72 h of the reperfusion stage, being lowest at 24 h after reperfusion, compared to the phase of ischemia by Western blotting." (PMID 37693644, 2023). "Although the rest of 16 causal genes identified by the integrative analysis were only replicated in one or two analyses, some of them (e.g. ALDH2, CDK6, HDAC9, and SLC44A2) were previously reported linked to stroke, which also demonstrate the reliability of our integrative analysis in a way." (PMID 35449099, 2022). "Studies have found a link between stroke and ALDH2, another aldehyde dehydrogenase." (PMID 36258220, 2022). "Activation of ALDH2 by Alda-1 restores ALDH2 activity and attenuates oxidative stress-induced injury in various animal models of atherosclerosis, Parkinson’s disease, ischemia/reperfusion injury, heart failure, and stroke." (PMID 33597876, 2020). "In recent years, one research showed that carrying the wild-type allele of the ALDH2 polymorphism increased stroke risk among Korean men, but not in Korean women." (PMID 29254215, 2017). "In recent years, the activation of the ALDH2 pathway have been reported serving as a useful index in the identification of stroke-prone participants, and the ALDH2 pathway may be a potential target for the therapeutic intervention in ischemic stroke." (PMID 29254215, 2017). "ALDH2 may have the same effect on cerebral infarction as on stroke, and cerebral infarction is one of the most common types of ischemic stroke." (PMID 29254215, 2017). "Consequently, targeting ALDH2 for therapeutic purposes may represent a promising approach to prevent stroke-related damage." (PMID 40026415, 2025).
Stroke (continued). "A recent large-scale study (168,050 participants) confirmed the association between ALDH2 rs671 and alcohol consumption, which is highly relevant to AUD status, in Chinese population, and found it relevant to multiple comorbidities includes liver cirrhosis, stroke and gout." (PMID 40857241, 2025). "However, ALDH2 activation or overexpression protected the brain against stroke in rats." (PMID 26599441, 2015). "We examined the relationship among stroke, alcohol consumption, potential confounding factors, and SNPs rs1229984 and rs671 in two important alcohol metabolizing genes, ADH1B and ALDH2, respectively." (PMID 34051793, 2021). "At gene level, few were differentially expressed: ALDH2, ALOX5AP, F13A1, and IMPA2 (males, all stroke); ITGB3 (females, cardioembolic); ADD1 (males, atherosclerotic); F13A1, IMPA2 (males, lacunar); and WNK1 (females, lacunar)." (PMID 33193047, 2020). "To further explore the mechanism by which ALDH2 mediated the acute stroke injury, we subsequently evaluated the phosphorylated JNK (p-JNK) expression and found that it was stroke that mainly increased p-JNK expression." (PMID 32210721, 2020). "Previous animal stroke studies have reported that decreased ALDH2 was correlated with higher levels of 4-HNE and MDA, and found that ALDH2 protected against stroke by clearing 4-HNE." (PMID 29245933, 2017). "ALDH2*2 carriers with nonheavy drinking exhibited the latest age at stroke onset, followed by *1/*1 carriers with nonheavy drinking." (PMID 41324337, 2026). "Unlike ALDH2, the function of ALDH7A1 is not well understood and no literature has described its association with stroke so far." (PMID 36258220, 2022). "In stroke patients with or without PSE, the ALDH2*2 of rs671 was associated with higher levels of plasma 4-HNE." (PMID 25313998, 2014). "Our results provide the first evidence that the carriers of ALDH2*2 have increased 4-HNE levels after stroke with or without PSE." (PMID 25313998, 2014). "Furthermore, we identified ICA1L, CAND2, and ALDH2 from comprehensive analyses, including non-lacunar stroke brain PWAS and colocalization, and ICA1L was supported at the brain transcriptional level." (PMID 35733147, 2022). "However, protein kinase C does not exert a neuroprotective effect in ALDH2-knockdown rats after stroke." (PMID 34025411, 2021).